INS (insulin)
Diseases named in the same sentence as INS in open-access papers (continued):
Sharing a sentence is not in itself a finding about the gene and the disease.
Hypoglycemia (continued). "In elderly individuals with T1DM, age-related decline in renal function further contributes to hypoglycemia risk by reducing insulin clearance and impairing renal gluconeogenesis, thereby prolonging insulin action and diminishing glucose recovery capacity." (PMID 41473654, 2025). "Hypoglycaemia has a very broad differential diagnosis ranging from very common causes, such as exogenous insulin use, to rare causes, such as paraneoplastic syndromes." (PMID 39931615, 2025). "The most common ADRs were hypoglycemia and bleeding, which are often associated with the use of regular insulin and antithrombotic agents." (PMID 40463907, 2025). "Insulinomas, the most common functional pancreatic neuroendocrine tumors, cause hypoglycemia due to excessive insulin production, leading to severe clinical symptoms like coma or death." (PMID 40405975, 2025). "Long-acting basal insulins (glargine U-100 or detemir) reduce the risk of symptomatic and nocturnal hypoglycemia compared with NPH insulin." (PMID 41012462, 2025). "Further analysis of signal strength revealed that hypoglycemia-related events were the most significant signal across both populations, highlighting hypoglycemia as the primary safety concern associated with insulin therapy." (PMID 40997126, 2025). "Nowadays, the condition is characterized as an autoimmune disease manifesting with recurrent hypoglycemia in association with elevated levels of serum insulin and the presence of insulin autoantibodies." (PMID 39968421, 2025). "Of the three drugs (insulin, SUs, and GLs) that pose a high risk of hypoglycemia when used alone, the proportion of prescriptions for insulin and SUs decreased monotonically from 2013 to 2022." (PMID 40777704, 2025). "LPS administration to rodents has been shown to induce a rapid early hypoglycemia that is associated with enhanced insulin secretion." (PMID 41093076, 2025). "For exercise or other factors that can predispose to hypoglycaemia, Omnipod 5 has an activity feature, which sets a temporary target glucose to 150 mg/dL, and insulin delivery is less aggressive." (PMID 39526053, 2024). "Despite the seemingly decreasing rate of hypoglycaemia-related hospitalisation, the older antidiabetic agents (insulin and sulfonylureas) were still reported to be associated with hypoglycaemia-related hospital admissions or ED visits in older adults." (PMID 38256662, 2024). "Hemodialysis-dependent patients are at risk of hypoglycemia because of the prolonged effect of insulin, which can outlast the duration of dextrose in the bloodstream." (PMID 39274318, 2024). "In some circumstances, the leakage of light would induce considerable amounts of insulin release from the engineered β‐cells, which would cause hypoglycemia." (PMID 38751366, 2024). "Only participants on multiple daily insulin injections (instead of insulin pump) were significantly associated with severe hypoglycaemia (insulin pump, β = −2.29; 95% CI, −4.41 to −0.17; p=0.03)." (PMID 40302962, 2024). "Conversely, elevated insulin levels (hyperinsulinemia), a major cause of hypoglycemia, are frequently seen in cases of severe malarial hypotension." (PMID 39492784, 2024). "It is becoming increasingly apparent that the incorrect administration of insulin potentially contributes to an increased risk of unexpected hypoglycemia, glucose variability, and failure to achieve the desired glycemic goal." (PMID 39457586, 2024). "Patients with impaired renal function experience a delay in insulin clearance, complicating the adjustment of insulin dosing and elevating hypoglycemia risk." (PMID 39850482, 2024). "He failed a fast within 4 hours, with BG of 48 mg/dL (2.7 mmol/L) and insulin level of 4.6 μIU/mL (24.6 pmol/L) (diagnostic at the time of hypoglycemia >1.25 μU/mL [8.7 pmol/L])." (PMID 39170749, 2024). "With a low risk of hypoglycemia, weekly basal insulin injections should improve patients' quality of life, treatment adherence, and clinical inertia." (PMID 39211720, 2024).
Hypoglycemia (continued). "The elevated glucose and incretin hormone levels after a meal are likely attributed to the increased intensity of nutrient flow due to anatomical changes, potentially causing an overcompensation of insulin secretion and subsequent hypoglycemia." (PMID 39153140, 2024). "Both inpatient hypoglycaemia and severe hypoglycaemia were associated with increased length of stay adjusted for insulin use, age, CFS, and BMI." (PMID 38387535, 2024). "Intensive insulin treatment, leading to lower HbA1c levels, has been associated with a threefold increase in hypoglycemia frequency." (PMID 39539363, 2024). "In CREED trail, similar results were observed where patients on insulin regimens were having more risk for hypoglycemia as compared to those who were on oral antidiabetic medications." (PMID 38827884, 2024). "Insulin therapy affects weight loss in diabetic individuals, triggering appetite, causing hypoglycemia and increasing body fat." (PMID 38429842, 2024). "Diazoxide, a commonly used treatment in patients with hypoglycaemia, works by opening K-ATP channels on the β-cells, causing re-polarisation of the membrane, and thereby leading to a decrease in insulin secretion." (PMID 39153498, 2024). "Sulfonylureas, although effective in stimulating insulin secretion, carry risks such as hypoglycemia, hyperinsulinemia, and a possible association with increased cancer risk." (PMID 39720591, 2024). "The results support the recommendation not to excessively lower glucose levels during the first hours of insulin treatment, with particular caution in patients at high risk of hypoglycemia during the IIITP (especially those with low BMI)." (PMID 38594758, 2024). "Intensive insulin therapy increases the risk of hypoglycemia while maintaining normal blood glucose in T1DM patients." (PMID 38872219, 2024). "By bypassing insulin, patients are at lower risk of hypoglycemia, weight gain, and hepatic injury compared to other diabetic medications." (PMID 38910717, 2024). "This is relevant as most professional societies recommend insulin therapy, which carries an inherent risk of hypoglycaemia, as the cornerstone of glycaemic management in hospitalised individuals." (PMID 38953925, 2024). "Prolonged use of insulin in people with T1DM during Ramadan carries a risk of severe hypoglycemia, hyperglycemia, and ketoacidosis due to the long hours of fasting." (PMID 36896906, 2024). "Such flexibility helps reduce the risk of hypoglycemia, particularly at night, by fine-tuning insulin administration." (PMID 39310514, 2024). "It should be noted that the suitable sweeteners for veterinary medicine are saccharin or sorbitol, since, for example, xylitol can cause severe hypoglycemia in dogs, due to the massive generation of insulin by the pancreas." (PMID 38794238, 2024). "ADA standards of care are now recommending AID systems (for those with T1D) and other advanced insulin delivery devices such as connected pens for older adults to reduce the risk of hypoglycemia." (PMID 39351525, 2024). "This allows for the early initiation of insulin treatment for those who fear needle injections, and early insulin treatment is associated with effective glycemic control with minimal weight gain and hypoglycemia, thus reducing disease-associated complications." (PMID 39170740, 2024). "The non-sulfonylurea secretagogues were introduced in the 1990s and enhance insulin secretion in a more glucose-dependent manner, which reduces the risk of hypoglycemia compared to sulfonylureas." (PMID 39766270, 2024). "Two patients had their pre-treatment insulin permanently ceased due to hypoglycemia in the context of large weight loss." (PMID 38392055, 2024). "Sulfonylureas and meglitinides, which are oral insulin secretagogues, carry an inherent risk of causing hypoglycemia." (PMID 39199594, 2024). "Another cause of hypoglycemia with insulin and C-peptide level discrepancy is insulin autoimmune syndrome (IAS) [,6]." (PMID 39071705, 2024).
Hypoglycemia (continued). "Renal dysfunction increases the risk of hypoglycaemia via reduced insulin clearance, decreased gluconeogenesis during uraemia and increased glucose uptake of red blood cell during haemodialysis." (PMID 38871123, 2024). "After adjusting for potential confounders, hypoglycemia during the initial intravenous insulin therapy phase remained associated with mortality (hazard ratio 2.10, 95% CI 1.27–3.46, p = 0.004)." (PMID 38594758, 2024). "This mainstay treatment of multiple daily insulin injections has the inherent risk of potentially life-threatening hypoglycemia, for those with impaired awareness." (PMID 39553396, 2024). "If we consider the effect from a health or performance perspective, there is an increased risk of hypoglycemia due to greater insulin release." (PMID 39420894, 2024). "Once-weekly insulins provide a unique opportunity to simplify basal insulin therapy and to allow good glycaemic control with a low risk of hypoglycaemia." (PMID 38679644, 2024). "Unintentional IM injection consequently results in improper insulin absorption and is associated with an increased likelihood of frequent and unexplained events of hypoglycemia." (PMID 38304656, 2024). "The “smart” glucose-responsive mechanism prevents insulin overdosage and reduces the risk of hypoglycemia." (PMID 39065795, 2024). "This gradual glucose release reduces the need for both endogenous and exogenous insulin, subsequently lowering the risk of hypoglycemia." (PMID 39203739, 2024). "The multipathological context should be systematically considered when designing studies because multiple medication use (eg, sulfonylureas and insulin) can cause iatrogenic hypoglycemia and influence the clinical parameters." (PMID 38477979, 2024). "Although insulin is the gold standard treatment during pregnancy, the risk of hypoglycemia and weight gain, as well as the financial burden, maintenance requirements and patient education time, hinder patient compliance and impede treatment acceptance." (PMID 37798604, 2024). "TRPC5-deficient animals exhibit striking parallels to PACAP-deficient mice in terms of recovery from insulin-induced hypoglycemia." (PMID 39375537, 2024). "In Lean-NGT individuals, there is a time course increase in ICR, thus constraining plasma insulin concentrations, and possibly in response to the complete postprandial suppression in glucagon, thereby minimising the risk of hypoglycaemia." (PMID 39138690, 2024). "Gestational diabetes mellitus leads to a hyperglycaemic intrauterine environment, which results in a transient amplified insulin response in the newborn, causing hypoglycaemia." (PMID 38609891, 2024). ",7, 8, 9 At the same time, release of the insulin resistance and suppression of the insulin secretion caused by excessive catecholamine secretion by pheochromocytoma can lead to hypoglycemia." (PMID 39384339, 2024). "The limitations of early insulin formulations, such as unpredictable absorption, rigid dosing regimens, and an increased risk of hypoglycemia, highlighted the need for improved therapies." (PMID 39734941, 2024). "The use of ultrarapid insulin (FiAsp®) (URI) vs. rapid insulin (RI) analogs was associated with less hypoglycemia events (7.1 vs. 13.6%; p = 0.005) and TBR70 (1.7 ± 6.9 vs. 4.6 ± 13.9%; p = 0.003)." (PMID 39062173, 2024). "Hypoketotic hypoglycemia due to dysregulated insulin secretion is the most common cause of persistent hypoglycemia in children." (PMID 39483531, 2024). "This is a promising finding, since insulin, although effective in hyperglycaemic control for many patients, is associated with hypoglycaemia and weight gain." (PMID 38894744, 2024). "Icodec, compared to Glargine U100, was administered daily and achieved a non-inferiority endpoint that improved glucose control with a similar risk of level 2 and 3 hypoglycemia in insulin-naïve T2D individuals." (PMID 39200316, 2024).
Hypoglycemia (continued). "Sulfonylureas, thiazolidinediones, and insulin can significantly improve glycemic control, but all three can cause weight gain, and sulfonylureas and insulin analogs can also cause a high risk of hypoglycemia." (PMID 39598478, 2024). "Regarding safety outcomes, although the risk of level 1 hypoglycemia was increased by 42% with once-weekly insulin injections, the risk of clinically significant or severe hypoglycemia was similar to that with once-daily insulin injections." (PMID 39629047, 2024). "Since functional membrane β-cell KATP channels are required for the normal regulation of insulin secretion, abnormal KATP channels due to genetic variants lead to uncontrolled insulin secretion and persistent hypoglycemia." (PMID 38792494, 2024). "The primary cause of tardive hypoglycemia has been largely linked to the heightened initial phase of insulin secretion as a result of IR." (PMID 38655176, 2024). "People with T1D treated with five or more daily insulin injections were shown to be at reduced risk of severe hypoglycemia compared with subjects on fewer daily injections." (PMID 38894740, 2024). "The concomitant use of smart pens and CGM has the potential to improve adherence to intended insulin dosing, detect accidental incorrect dosing and reduce the risk of problematic hypoglycaemia." (PMID 39138689, 2024). "In ESKD, the risk of hypoglycaemia is heightened owing to impaired kidney gluconeogenesis, decreased kidney degradation and clearance of insulin, increased erythrocyte glucose uptake during haemodialysis, and nutritional deprivation." (PMID 39112642, 2024). "Cortisol, an insulin counter-regulatory hormone, plays a pivotal role in maintaining euglycemia; deficiency predisposes to the development of hypoglycemia." (PMID 38957156, 2024). "DPP-4 inhibitors, with their glucose-dependent insulin secretion, low risk of hypoglycemia, and weight neutrality, provide an attractive option for these patients." (PMID 39768866, 2024). "Theoretically, the system should suspend the insulin delivery as long as needed to minimize the risk of hypoglycemia, which occurred more frequently after SB administration in our study group (on sensor-augmented pump therapy)." (PMID 38257156, 2024). "Further, risk of hypoglycemia is lower with Gla-100 than Neutral Protamine Hagedorn but comparable to insulin detemir." (PMID 36896906, 2024). "Clinical studies conducted prior to 2010 had established the comparable glucose-lowering efficacy, yet the significantly lower risk of hypoglycemia with Gla-100 compared to neutral protamine Hagedorn (NPH) insulin." (PMID 36896906, 2024). "Patients with T2DM from Southeast Asia appear to have an elevated risk of hypoglycemia, as these patients are more often treated with a premixed insulin formulation, are younger, and have a lower BMI than those of their counterparts from Western countries." (PMID 38801705, 2024). "Hypoglycemia: The risk of hypoglycemia is increased with the SGLT2 concomitant administration of insulin secretagogues, such as sulfonylureas or insulin." (PMID 39861067, 2024). "Since becoming reliant on insulin, a significant worry, particularly for those who lived alone, was the risk of nocturnal hypoglycaemia." (PMID 38778253, 2024). "Congenital hyperinsulinism (CHI) is characterized by dysregulated insulin secretion causing hypoglycemia and consequent brain damage." (PMID 37930757, 2024). "Persistent hypoglycemia is caused by this increased insulin secretion, especially when fasting or exercising when glucose availability is restricted." (PMID 39723310, 2024). "In contrast, insulin therapy is associated with a significantly higher risk of hypoglycemia, particularly in intensive treatment regimens." (PMID 39723311, 2024). "Hypoglycemia is a risk for people with T2D being treated with insulin, with reported rates of severe hypoglycemia approximately 2.5 events per person per year." (PMID 39877917, 2024).
Hypoglycemia (continued). "For patients at high risk of hypoglycemia, such as those on insulin therapy, Continuous Glucose Monitoring (CGM) is strongly recommended." (PMID 39274537, 2024). "One study found that rates of sulfonylurea and/or insulin de-intensification were less than 50% after hypoglycaemia-associated emergency visits or hospitalisations." (PMID 39407915, 2024). "Late dumping syndrome, which occurs 1 to 3 h after eating, is characterized by hypoglycemia, weakness, sweating, dizziness, and disorientation caused by an increased insulin response owing to fast sugar absorption in the small intestine." (PMID 39555226, 2024). "After single-daily injections, the day-to-day variability in response and the risk of nocturnal hypoglycemia are lower compared to insulin glargine." (PMID 39734941, 2024). "Insulin causes hypoglycemia by causing intracellular shifting of glucose into muscle and adipose tissue." (PMID 38827803, 2024). "This disorder involves elevated insulin production during meals, which causes modest to severe hypoglycemia." (PMID 39555226, 2024). "Sulfonylureas, though effective in stimulating insulin secretion, are associated with higher risks of hypoglycemia, hyperinsulinemia, and possibly cancer." (PMID 39720591, 2024). "Without this partnership, there was likely to be a disconnect between the nurses who complete the survey and identify the cause of hypoglycemia and the clinical staff who have the capacity to adjust the patients’ glycemic management (e.g., insulin doses)." (PMID 38283395, 2024). "These aim to prevent a sudden rise in blood glucose that would cause a rapid insulin release and subsequent hypoglycaemia." (PMID 39153498, 2024). "Insulin, while the most potent glucose-lowering agent, carries a higher risk of hypoglycemia and weight gain." (PMID 39723311, 2024). "Exercise can increase the risk of hypoglycemia via several mechanisms: increased glucose consumption, depletion of glycogen stores, increased insulin sensitivity, and exercise-induced counterregulatory hormone deficits." (PMID 38894740, 2024). "These formulations however are associated with some drawbacks such as the need to match insulin administration to consistent feeding, marked day‐to‐day variability, and increased risk of hypoglycemia." (PMID 38831362, 2024). "Thereby, mechanistically speaking, the probability that at standard dosing insulin icodec causes excessive acute glucogenic effects leading to hypoglycemia events compared to once-daily insulin seems to be low." (PMID 38213906, 2024). "On the one hand, chronic insulinoma secretes too much insulin, causing patients to experience recurrent hypoglycemia, while recurrent episodes of hypoglycemia cause patients to avoid hypoglycemic symptoms by increasing their food intake." (PMID 38334891, 2024). "Taken together, neither lower plasma concentrations of glucocorticoids or glucagon nor a reduced systemic response to these hormones are responsible for the phenotype of aggravated insulin-induced hypoglycemia in TRPC5-deficient mice." (PMID 39375537, 2024). "Compared to prior insulin formulations, modern basal insulin formulations are very effective and are associated with a reduced risk of hypoglycemia." (PMID 39211720, 2024). "Short-acting insulin has a delayed onset, peaking 2–3 h post-injection, and can cause hypoglycemia due to prolonged action." (PMID 39065641, 2024). "While evaluating for the cause of hypoglycemia, after excluding common causes like insulin use or sepsis, other causes involving endogenous hypoglycemia need to be evaluated." (PMID 39188435, 2024). "CSII provides better flexibility in basal insulin adjustments and management of EXE-associated hyper- or hypoglycemia than other insulin delivery methods in the management of early-onset and late-onset hypoglycemia after EXE." (PMID 38542818, 2024).